OR51D1 (olfactory receptor family 51 subfamily D member 1)
Description:
Odorant receptor.
Synonyms: OR51D1Q; OR11-14
Tractability: Antibody: its Gene Ontology location is reachable by antibodies, with high confidence; UniProt places it where antibodies can reach, with medium confidence; UniProt predicts a signal peptide or a membrane-spanning region.
Gene: Protein-coding gene on chromosome 11 (4,637,477 to 4,643,060, forward strand). Ensembl gene ENSG00000197428.
Subcellular location: Cell membrane
Pathways (Reactome):
Sensory Perception: Expression and translocation of olfactory receptors; Olfactory Signaling Pathway
Gene Ontology:
Molecular function: olfactory receptor activity; G protein-coupled receptor activity; signaling receptor activity
Biological process: cellular response to lipid; detection of chemical stimulus involved in sensory perception of smell; G protein-coupled receptor signaling pathway; system process
Cellular component: plasma membrane; membrane
Genetic constraint (gnomAD): Loss-of-function variants: 10 observed, 11.61 expected, observed/expected ratio (o/e) 0.86, 90% interval 0.53 to 1.46. The upper end of that interval is the gene's LOEUF score, 1.46, which puts it in group 6 of 6, group 1 being the genes least tolerant of losing a copy. Missense variants: 452 observed, 418.64 expected, observed/expected ratio (o/e) 1.08, 90% interval 1 to 1.17. Synonymous variants: 187 observed, 171.26 expected, observed/expected ratio (o/e) 1.09, 90% interval 0.97 to 1.23.
Homologues: Orthologues: chimpanzee OR51D1 (98% identical), rabbit OR51D1 (91% identical), mouse Or51d1 (88% identical), rat Or51d1 (87% identical), tropical clawed frog or51ao2 (52% identical). Paralogues in human: OR51E1 (56% identical), OR51E2 (55% identical), OR51G2 (48% identical), OR51I2 (48% identical), OR52K1 (47% identical), OR52L1 (47% identical), OR52K2 (46% identical), OR51A4 (46% identical), OR51A2 (44% identical), OR52M1 (44% identical), OR51A7 (44% identical), OR52D1 (44% identical), and 39 more.